TMEM52B (transmembrane protein 52B)
Synonyms: C12orf59; FLJ31166
Tractability: Antibody: UniProt predicts a signal peptide or a membrane-spanning region.
Gene: Protein-coding gene on chromosome 12 (10,170,512 to 10,191,807, forward strand). Ensembl gene ENSG00000165685.
Subcellular location: Membrane
Subcellular location (Human Protein Atlas): Focal adhesion sites
Gene Ontology:
Molecular function: protein binding
Cellular component: extracellular exosome; membrane
Genetic constraint (gnomAD): Loss-of-function variants: 7 observed, 8.74 expected, observed/expected ratio (o/e) 0.8, 90% interval 0.45 to 1.49. That is too few expected variants to judge how well the gene tolerates losing a copy. Missense variants: 162 observed, 148.15 expected, observed/expected ratio (o/e) 1.09, 90% interval 0.96 to 1.25. Synonymous variants: 68 observed, 59.59 expected, observed/expected ratio (o/e) 1.14, 90% interval 0.94 to 1.4.
Homologues: Orthologues: chimpanzee TMEM52B (99% identical), macaque TMEM52B (90% identical), dog TMEM52B (83% identical), mouse Tmem52b (80% identical), pig TMEM52B (78% identical), rat Tmem52b (78% identical), guinea pig TMEM52B (77% identical).
Diseases named in the same sentence as TMEM52B in open-access papers:
TMEM52B is named in the same sentence as 18 diseases in open-access papers, as found by Europe PMC text mining. Sharing a sentence is not in itself a finding about the gene and the disease. The quoted sentences say what the papers report.
renal cell carcinoma (4 papers, 2016 to 2024). "In that study, decreased TMEM52B expression was correlated with poor survival and von Hippel-Lindau mutations in renal cell carcinoma patients, suggesting that decreased TMEM52B expression may promote renal carcinogenesis." (PMID 33641663, 2021). "Consistent with our results, it has been recently reported that the downregulation of TMEM52B correlated with poor survival of renal cell carcinoma patients." (PMID 33641663, 2021).
colon carcinoma (3 papers, 2021 to 2024). "Suppression of TMEM52B in colon cancer cells promoted cancer cell epithelial-mesenchymal transition (EMT), invasion, and survival in vitro." (PMID 33641663, 2021). "TMEM52B mRNA was highly expressed in SW480sub (a subclone of SW480, displaying elevated cell-matrix adhesion capacity), HCT-15, and Caco-2 colon cancer cells and was moderately expressed in MKN28 (gastric cancer), SW480 (colon cancer) cells." (PMID 33641663, 2021).
gastric cancer (3 papers, 2021). A primary or metastatic malignant neoplasm involving the stomach. "In contrast, TMEM52B is also associated with poor survival of gastric cancer patients, and reported to promote gastric cancer cell invasiveness and metastatic capacity." (PMID 33641663, 2021).
esophageal squamous cell carcinoma (2 papers, 2022 to 2024). Esophageal squamous cell carcinoma (ESCC) is a type of esophageal carcinoma (EC) that can affect any part of the esophagus, but is usually located in the upper or middle third. "Given that we had previously shown that TMEM52B promotes the progression of esophageal squamous cell carcinoma (ESCC) by increasing the EMT of ESCC cells, we followed TMEM52B further as a potential Oncogenic factor in NPC." (PMID 38940427, 2024).
renal carcinoma (2 papers, 2016 to 2024). A carcinoma arising from the epithelium of the renal parenchyma or the renal pelvis. "A study found that reduced TMEM52B expression was associated with unfavorable survival outcomes and von Hippel-Lindau mutation in patients with renal cancer, suggesting the downregulation of TMEM52B expression and the downregulation of TMEM52B in the occurrence of renal cancer." (PMID 38675412, 2024).
breast carcinoma (1 paper, 2021). "We also found that high TMEM52B expression in lung and breast cancer patients was significantly correlated with increased overall survival and relapse-free survival, respectively, when survival within previously published data sets was analyzed using the KM-plotter." (PMID 33641663, 2021).
kidney cancer (1 paper, 2021). Primary or metastatic malignant neoplasm involving the kidney. "We also found that kidney cancer patients with tumors that highly expressed TMEM52B (Z > 1.5) had a significantly better overall survival rate than the remaining patients (Z ≤ 1.5) from the analysis of TCGA-generated kidney cancer data (TCGA, Firehose Legacy)." (PMID 33641663, 2021).
liver cancer (1 paper, 2021). An epithelial or non-epithelial malignant neoplasm that arises from the liver. "TMEM52B expression in liver cancer patients showed a tendency for a positive correlation with increased relapse-free survival." (PMID 33641663, 2021).
nasopharyngeal carcinoma (1 paper, 2024). A carcinoma arising from the nasopharyngeal epithelium. "TMEM52B represents a promising biomarker for early diagnosis and prognostic prediction in nasopharyngeal carcinoma (NPC)." (PMID 38940427, 2024). "Transmembrane protein 52B (TMEM52B), a newly identified tumor‐related gene, has been reported to regulate various tumors, yet its role in nasopharyngeal carcinoma (NPC) remains unclear." (PMID 38940427, 2024).
ovarian carcinoma (1 paper, 2024). A malignant neoplasm originating from the surface ovarian epithelium. "Interestingly, SNHG25, known for promoting ovarian cancer progression, and TMEM52B, associated with EGFR and E-cadherin modulation and tumor/metastasis suppression, significantly decreased with KPT-9274 treatment." (PMID 38424218, 2024).
rectal cancer (1 paper, 2021). A primary or metastatic malignant neoplasm that affects the rectum. "Clinical data showed that high TMEM52B expression correlated with increased patient survival in multiple types of cancer, including breast, lung, kidney, and rectal cancers, and suggested a correlation between TMEM52B and E-cadherin." (PMID 33641663, 2021).
tumor (7 papers, 2014 to 2026). "Transcriptomic analysis of NPC cell lines reveals frequent overexpression of TMEM52B, and immunohistochemical results show that TMEM52B is associated with advanced tumor stage, recurrence, and decreased survival time." (PMID 38940427, 2024). "This study highlights the novel functions and underlying mechanisms of TMEM52B, suggesting its prominent role in tumor progression." (PMID 33641663, 2021). "Together, these results demonstrate that TMEM52B knockdown significantly inhibits NPC tumor growth and metastasis." (PMID 38940427, 2024). "To explore the role of tumor‐related gene TMEM52B in NPC, we conducted transcriptome sequencing of three Normal nasopharyngeal epithelial cell (NPEC) and eight NPC cell lines." (PMID 38940427, 2024). "Here we report that suppression of TMEM52B in cancer cells increases cell survival and invasion in vitro, and enhances tumor growth and early metastasis in vivo." (PMID 33641663, 2021). "The effects of TMEM52B on tumor growth and metastasis were investigated in vitro and in vivo, and the underlying biological and molecular mechanisms involved in this process were evaluated." (PMID 33641663, 2021). "Tumor growth was significantly increased in mouse xenografts with TMEM52B-suppressed cells compared to those with scrambled shRNA-transfected control cells." (PMID 33641663, 2021). "Immunostaining of tumor sections from mice injected with TMEM52B-suppressed cells showed higher levels of proliferative Ki67-positive cells compared with the control-treated mouse tumors." (PMID 33641663, 2021). "Among the 3415 upregulated genes, TMEM52B, previously identified in our report as a tumor suppressor in RCC, showed a significant increase of more than 20‐fold (24.66) in all eight NPC cell lines compared to normal NPEC cells, real‐time PCR and western blotting confirmed this observation." (PMID 38940427, 2024). "Based on the expression levels of TMEM52B in cancer tissues, we divided all NPC patients into high and low expression groups; high TMEM52B expression was significantly associated with advanced tumor node metastasis stage and recurrence." (PMID 38940427, 2024). "In this study, we aimed to understand whether the novel tumor‐related gene TMEM52B can regulate the occurrence and development of NPC and the underlying molecular mechanism." (PMID 38940427, 2024). "It is possible that the soluble E-cadherin generated by TMEM52B suppression may exert its pro-tumorigenic activity directly to cancer cells and stroma cells in the tumor microenvironment, although it needs further investigation." (PMID 33641663, 2021). "It is possible that TMEM52B functions as a tumor-suppressor that could potentially be used as a novel prognostic marker for cancer." (PMID 33641663, 2021). "Similarly, TMEM52B function and its precise molecular basis requires further exploration during both tumor development and in normal tissues." (PMID 33641663, 2021). "To investigate whether TMEM52B influences NPC tumor growth in vivo, we performed xenograft experiments in BALB/c nude mice via subcutaneous inoculation of SUNE‐1 cells transfected with either control‐shRNA‐expressing lentiviral vector (LV‐shCtrl) or LV‐shTMEM52B." (PMID 38940427, 2024). "Therefore, the downregulation of intact E-cadherin and the production of soluble E-cadherin, mediated by TMEM52B suppression, may contribute to the accelerated malignancy aggressiveness and tumor progression through both autocrine and paracrine mechanisms." (PMID 33641663, 2021). "The knockdown of TMEM52B promotes epithelial-mesenchymal transition (EMT), invasion, and cell survival in vitro, and it enhances tumor growth and circulating tumor cell levels in vivo." (PMID 41596760, 2026). "We report here that TMEM52B plays a role in cancer cell invasion and survival, in an EGFR-dependent manner, to reduce tumor growth and early metastasis." (PMID 33641663, 2021). "Thus, a reduction in TMEM52B expression may contribute to tumor progression." (PMID 33641663, 2021).
tumor (continued). "E-cadherin was substantially detected and vimentin was not apparently detected in tumor sections of mice injected with TMEM52B-expressing control cells, while vimentin but not E-cadherin was moderately detected in tumor sections of mice injected with TMEM52B-suppressed cells." (PMID 33641663, 2021). "Hence, we speculate that irrespective of whether TMEM52B functions as a tumor suppressor or an oncoprotein, TMEM52B‐P20 has a more consequential function." (PMID 38940427, 2024).
cancer (5 papers, 2016 to 2026). A tumor composed of atypical neoplastic, often pleomorphic cells that invade other tissues. "The clinical data analysis showed that TMEM52B expression was positively correlated with the increased survival of patients with several cancer types." (PMID 33641663, 2021). "Together, these results suggest that TMEM52B suppression promotes cancer cell invasion and survival through activation of ERK1/2, JNK, and AKT signaling pathways." (PMID 33641663, 2021). "Clinically, high TMEM52B expression correlated with increased survival among patients with varying types of cancer, implicating the use of TMEM52B as a potential prognostic biomarker." (PMID 33641663, 2021). "Together, these results suggest that TMEM52B suppression promotes cancer cell invasion and survival mainly through EGFR activation and internalization although we cannot completely rule out the possibility that other receptors are involved in TMEM52B function." (PMID 33641663, 2021). "Drugs targeting these TMEM52B isoforms may offer therapeutic benefits to cancer patients with varying degrees of metastasis." (PMID 38940427, 2024). "To explore the expression of TMEM52B in various cancer cell lines, we performed RT-qPCR analysis." (PMID 33641663, 2021). "We examined whether TMEM52B expression correlated with E-cadherin expression in various cancer cell lines and in human cancers." (PMID 33641663, 2021). "For example, full-length or partial fragments of TMEM52B may be candidates for an anti-cancer drug through gene therapy or administration of recombinant suppressor proteins or small molecule mimetics." (PMID 33641663, 2021). "However, general biological or cancer-biology functions for TMEM52B expression have yet to be determined." (PMID 33641663, 2021). "TMEM52B might therefore be exploited as part of a novel strategy for cancer treatment." (PMID 33641663, 2021). "We next explored whether TMEM52B overexpression suppressed cancer cell invasion and survival." (PMID 33641663, 2021). "TMEM52B suppression enhanced EGFR activation and the downstream MAPK and AKT signaling pathways, leading to cancer cell invasion and survival." (PMID 33641663, 2021). "However, the biological function of TMEM52B expression in cancer is largely unknown." (PMID 33641663, 2021). "Recently, broad TMEM52B expression was reported in normal human tissues, with high expression in kidney; however, its expression in a panel of cancer cell lines was not detectable." (PMID 33641663, 2021). "TMEM52B suppression reduces E-cadherin stability to produce soluble E-cadherin and enhances the activation and internalization of EGFR and its downstream signaling activity, leading to cancer cell invasion and survival." (PMID 33641663, 2021). "As a recently discovered gene, TMEM52B function in cancer has not been studied intensively." (PMID 38940427, 2024). "Whether TMEM52B exerts positive or negative influences by cancer type or in a context-dependent manner needs to be further explored." (PMID 33641663, 2021). "In addition, enforced expression of TMEM52B isoforms in HCT-116 cells, which display little to no TMEM52B expression, reduced phosphorylation of EGFR, AKT, JNK, ERK1/2, and c-Jun along with reduced cancer cell invasion and survival, confirming the effects of the TMEM52B isoforms." (PMID 33641663, 2021).
TMEM52B also shares sentences with these, for which no sentence is quoted: genitourinary cancer (2 papers); clear cell renal cell carcinoma (1); infection (1); non‐small cell lung cancer (1); thyroid cancer (1).